FGL1 (fibrinogen like 1)
Diseases named in the same sentence as FGL1 in open-access papers (continued):
Sharing a sentence is not in itself a finding about the gene and the disease.
tumor (continued). "Considering the importance of FGL1 in tumor immunity, it is worth determining whether FGL1 is acetylated and identifying the biological function of acetylation." (PMID 37115693, 2023). "Additionally, the binding of LAG-3 to the soluble liver-secreted Fibrinogen-Like protein 1 (FGL-1) has been shown to inhibit CD8+ T cell-mediated anti-tumor effects, but the significance of this interaction in hematologic malignancies remains to be elucidated." (PMID 37920162, 2023). "FGL1 may simultaneously serve as an oncogene and tumor suppressor gene in various cancers due to tumor heterogeneity." (PMID 37872170, 2023). "Our previous data showed that SIRT2 deacetylates and stabilizes FGL1, thus suppressing tumor immunity, suggesting that SIRT2 and acetylation of FGL1 may play an important role in the development of HCC." (PMID 37115693, 2023). "Both FGL1 and relative acetyl-K98 FGL1 levels correlated with tumor size." (PMID 37115693, 2023). "However, the authors did demonstrate enhanced tumor invasion by immune cells in response to FGL1 acetylation, and past research has shown FGL1–LAG-3 interaction." (PMID 37115694, 2023). "Increased FGL1 expression in HCC may result in CD8+ TRM cell exhaustion, causing tumor immune escape." (PMID 36993960, 2023). "Additionally, we found abundant expression of the LAG-3 ligands MHC-II and galectin-3 in diverse immune cell types, whereas FGL1 and LSECtin were minimally expressed by immune cells in the tumor microenvironment (TME)." (PMID 37795090, 2023). "In recent years, high FGL1 expression was also found in tumor cells." (PMID 37872170, 2023). "Briefly, after anesthesia with isoflurane, the mice were injected in the left hepatic lobe with PBS (referred to as the sham-operation group), 5 × 106 wildtype (WT) Hepa1-6 tumor cells (referred to as the control group), or 5 × 106Fgl1-KO Hepa1-6 tumor cells (referred to as the sh-Fgl1 group)." (PMID 36993960, 2023). "Blocking FGL1 can enhance the anti-tumor immune function of T cells and further inhibit tumor growth, and such anti-tumor effects could even be strengthened in combination with PD-L1 inhibitors." (PMID 35273912, 2022). "This suggests that the FGL1 level of CTC can reflect the expression of FGL1 in the primary tumor." (PMID 35273912, 2022). "CTC detection may serve as a promising replacement for determination of tumor tissue FGL1 expression and provide evidence for the application of immunotherapy." (PMID 35273912, 2022). "In addition, we performed FGL1 staining of tumor tissue sections and assessed the FGL1 expression with ImageJ software." (PMID 35273912, 2022). "Based on these data, it can be speculated that the FGL1 is linked to the progression and prognosis of HCC by functioning as a tumor suppressor." (PMID 35776395, 2022). "In metastatic NSCLC characterized by high plasma FGL1 levels, the poor outcome after anti-PD-1 treatment suggests that FGL1 may play a role in tumor immune resistance." (PMID 36291069, 2022). "In addition, we have also found that the detection of peripheral blood CTC can reflect the FGL1 expression level of the primary tumor." (PMID 35273912, 2022). "FGL1 expression was detected in circulating tumor cells of 40 patients (36.7%)." (PMID 35273912, 2022). "Moreover, FGL1 was positively associated with the CD3D expression and negatively associated with FOXP3, S100A9, and TPSB2 within the tumor site." (PMID 36268014, 2022). "Based on a univariate Cox regression analysis, tumor number, Edmondson grade, metastasis, HBsAg and FGL1 expression level could all be prognostic factors for HCC (P < 0.1)." (PMID 35776395, 2022). "In addition, we performed FGL1 staining on postoperative tissue sections of patients to analyze the relationship between tissue FGL1 expression levels and circulating tumor cell FGL1 expression levels." (PMID 35273912, 2022). "However, FGL1 expression not only affects hepatocyte regeneration but also regulates the growth and proliferation of tumor cells." (PMID 35776395, 2022).
tumor (continued). "It is of interest that FGL1 owns both pro-tumor and anti-tumor functions." (PMID 33867830, 2021). "The research potential of LAG3/FGL1 is enormous, understanding more about them may result in a broader implication, which may provide a novel strategy for tumor therapy." (PMID 35111155, 2021). "In this review, we summarize the substantial regulation mechanisms of FGL1 in physiological and pathological conditions, especially tumor epithelial to mesenchymal transition, immune escape and immune checkpoint blockade resistance, to provide insights for targeting FGL1 in cancer treatment." (PMID 34526102, 2021). "Furthermore, PD-L1, AMPK-α, Thr172, and FGL1 levels in tumor tissue were evaluated by immunohistochemistry analysis." (PMID 33632231, 2021). "High LAG3 and FGL1 expression boosts tumor growth by inhibiting the immune microenvironment." (PMID 35111155, 2021). "Based on in vivo experiments, loss of the FGL1/LAG3 interaction could be achieved by gene knockout or antibody blockade, and antitumor immunity could be promoted by stimulating tumor-infiltrating lymphocyte (TIL) activation and expansion in the TME." (PMID 34526102, 2021). "Therefore, our data elucidated that FGL1 exerts the biological function of promoting tumor cell migration, invasion, and metastasis by facilitating EMT process in ccRCC." (PMID 34956878, 2021). "While a study showed that FGL1 promotes HCC tumor formation by inhibiting the activation of antigen-specific T cells 15, another study found that FGL1 could inhibit the growth and proliferation of HCC, which runs counter to previous conclusions." (PMID 33867830, 2021). "LAG3 and FGL1 play significant roles in tumor therapy resistance." (PMID 35111155, 2021). "We found that FGL1 was upregulated in tumor tissues and plasma specimens of ccRCC patients." (PMID 34956878, 2021). "Moreover, LAG-3 can bind with the LSECtin, a member of the C-type lectin receptor superfamily, typically exposed on tumor cell membranes, and with the fibrinogen like protein 1 (FGL-1), which is part of the fibrinogen protein superfamily." (PMID 34357118, 2021). "In addition, the analysis of FGL1 in serum as a liquid biopsy is a simple and noninvasive alternative to surgical biopsies that allows doctors to gather a range of tumor-related information and provides clues to the most effective immunotherapy." (PMID 33633363, 2021). "We developed a pH-responsive hybrid biomimetic membrane-camouflaged PLGA nanoparticle system based on multiple tumor targets and low-pH-activated endosomal/lysosomal escape to co-deliver the FGL1/LAG3 blockade molecule, siFGL1, and immuno-metabolic adjuvant Met." (PMID 33632231, 2021). "Moreover, tumor immunity was stimulated by the antibody blocking the FGL1-LAG-3 interaction in the tumor microenvironment." (PMID 33633363, 2021). "This suggested that upregulation of FGL1 may have contributed to the progression of ccRCC by promoting tumor metastasis." (PMID 34956878, 2021). "Finally, we revealed that FGL1 stimulated tumor growth in vivo by increasing myeloid-derived CD11b+ and Ly6G+ immune cell infiltration in TME." (PMID 34956878, 2021). "Our data confirmed that knocking down FGL1 inhibits tumor growth in vivo." (PMID 34956878, 2021). "Hence, FGL1 is released at lower levels by HCC tumor tissues but at higher levels in other solid tumors." (PMID 34526102, 2021). "However, tumor volumes (P < 0.05) and tumor weights (P < 0.05) were significantly lower in FGL1-siRNA-treated mice and in mice treated with FGL1-siRNA and gefitinib than in mice treated with NC-siRNA or gefitinib alone." (PMID 32778129, 2020). "FGL-1 is produced and secreted by tumor cells and hepatocytes." (PMID 33374804, 2020). "Furthermore, compared to monotherapy, an anti-FGL1 mAb or anti-LAG-3 mAb in combination with an anti-B7-H1 mAb significantly reduces tumor burden and prolongs survival." (PMID 31681269, 2019). "Thus, FGL1 knockdown in vivo inhibited tumor proliferation by suppressing glycolysis." (PMID 41024301, 2025).
tumor (continued). "We simultaneously ectopically expressed Myc-tagged SAMD4B, Flag-tagged APOA2 and HA-tagged immune checkpoints that are mainly expressed in tumours (PD-L1, PD-L2, FGL1 or HMGB1) and demonstrated that overexpression of SAMD4B could reduce the protein level of APOA2." (PMID 38886351, 2024). "Interestingly, FGL1 may exert either anti-tumor activities or tumor-promoting effects, depending on the tumor type." (PMID 38903931, 2024). "Moreover, the tumor-penetrating peptide iRGD and the ROS-responsive nanoparticles were co-administered to further enhance the delivery efficiency of siFGL1 and siPD-L1, thereby significantly reducing the protein levels of FGL1 and PD-L1 in tumor cells." (PMID 37509610, 2023). "Moreover, blockade of the FGL1-LAG-3 interaction in the tumor microenvironment improve the antitumor immunity and enhances T cell responses as an immune escape mechanism and may have potential target for design a novel cancer immunotherapy." (PMID 38162657, 2023). "Note that we observed an upregulation of FGL1 mRNA levels in multiple types of cancer, implying that the weak response of patients to immunotherapy may be due to the inhibitory tumor microenvironment (TME)." (PMID 37115693, 2023). "Additionally, high FGL1 expression was associated with better overall survival in HCC patients, suggesting that FGL1 could function as a tumor suppressor." (PMID 35776395, 2022). "Thus, we considered that in addition to serve as an independent immune checkpoint gene, FGL1 may also be coexpressed with PD-L1 and further play a regulatory role in tumor immunity." (PMID 36268014, 2022). "The result showed that FGL1 expression was correlated with the infiltration of several immune cells in various types of malignancy, which indicates that there might be a relationship between FGL1 expression and tumor immune microenvironments." (PMID 35273912, 2022). "FGL1 may simultaneously serve as oncogene and tumor suppresser gene in various cancers." (PMID 35111155, 2021). "Furthermore, the reduction or nonexpression of FGL1 is significantly associated with the degree of tumor differentiation." (PMID 33968077, 2021). "We speculated that FGL1 may play an important role in modulating tumor innate immunity." (PMID 34956878, 2021). "However, the intracellular signaling pathways of LAG3 and FGL1, both of which play a role in the regulation of immune cell function, cytokine production, and tumor growth, remain unknown." (PMID 35111155, 2021). "Moreover, FGL1 was shown to be closely associated with tumor cell invasion and metastasis via acquisition of the EMT phenotype, which was underlined by bidirectional crosstalk between tumor cells and the surrounding TME." (PMID 34526102, 2021). "Importantly, FGL1 expression not only affects the regeneration of hepatocytes, but may also regulate the growth and proliferation of tumor cells due to its role in cell proliferation pathways." (PMID 32778129, 2020). "Additionally, three novel LAG-3 ligands have been reported: galectin-3, liver sinusoidal endothelial cell lectin (LSECtin), and fibrinogen-like protein 1 (FGL1) which are abundantly present in the tumor environment to help regulate and effectively abolish anti-tumor immunity of CD8+ T cells." (PMID 31569553, 2019). "Subcutaneous tumor-bearing nude mice showed that FGL1 knockdown in LLC and H226 cell lines significantly inhibited tumor proliferation (P < 0.05)." (PMID 41024301, 2025). "We collected 13 ICC tumor samples and performed qPCR to evaluate the expression of DCDC2 and FGL1, alongside an analysis of their correlation." (PMID 40533767, 2025). "Knockdown of CENPM also resulted in a decrease of ki67 positive cells and a decline of FGL1 levels, as shown by ki67 staining and immunofluorescence of ACC metastatic tumour nodules, respectively." (PMID 39778025, 2025).
tumor (continued). "Consumption of FBXO38 significantly increases the abundance of FGL1, inhibits CD8(+) T cell infiltration, and enhances tumour immune escape, thereby promoting NSCLC progression." (PMID 39865544, 2025). "The present study uncovered a DCDC2/ENO1/FGL1/LAG-3 axis and communication between ICC tumor cells and CD8+ T cells." (PMID 40533767, 2025). "Compared with hepatocytes, tumor cells, including Hepa1-6, MC38, and B16-F10 cells, expressed lower levels of Fgl1 mRNA and FGL1 protein, indicating that hepatocytes are the major source of FGL1 in the liver tumor microenvironment." (PMID 38973608, 2024). "In this study, we demonstrated that hepatocytes were the major source of FGL1 in the liver tumor microenvironment, since tumor cells, including Hepa1-6, MC38, and B16-F10 cells, expressed significantly lower levels of FGL1 than hepatocytes." (PMID 38973608, 2024). "Fibrinogen-like protein 1 (FGL-1) is a major LAG-3 functional ligand independent from MHC-II and induces a significantly reduced anti-tumor response." (PMID 39057061, 2024). "Accordingly, we demonstrated herein that NExT are naturally functionalized with diverse receptors (PD1, LAG3, TIM3) that can interact with their corresponding ligands (e.g., PDL1, Galectin-3, FGL-1, MHCII, Galectin-9, HMGB1, Ceacam-1) within the tumor." (PMID 38730475, 2024). "Studies have demonstrated that fibrinogen-like protein 1 (FGL-1), a critical ligand for LAG-3, can trigger T-cell suppression, facilitating tumor immune evasion." (PMID 39050882, 2024). "Lastly, the complexity of the tumor microenvironment and its potential influence on FGL1 and IMPDH1 regulation necessitate additional investigation to fully comprehend the interplay between these molecules and the tumor immune response." (PMID 38702629, 2024). "Fibrinogen-like protein 1 (FGL1), a ligand of the inhibitory receptor LAG-3, can induce LAG-3 clustering and has recently been considered a checkpoint for tumor immunotherapy." (PMID 38973608, 2024). "The binding of FGL1 and LAG-3 inhibits antigen-specific T cell immune response, and blocking the interaction between FGL1 and LAG-3 can reactivate the anti-tumor immune ability of T cells." (PMID 38177102, 2024). "The results showed that CD200, CD80 and TNFRSF14 were the highest in tumor tissues, CD274 (PDL1), CD86, LGALS9, NECTIN2, PDL2, PVR were lower than those in adjacent tissues but higher than those in normal tissues, and FGL1 was the lowest in tumor tissues." (PMID 39120585, 2024). "FGL-1 secreted by tumor cells within the TME can bind to LAG-3 on TILs, thereby inhibiting the anti-tumor activity." (PMID 39660130, 2024). "Blockade of the FGL1/LAG-3 interaction by anti-FGL1 mAb or anti–LAG-3 mAb enhances antitumor immunity and shows therapeutic effects on an established mouse subcutaneous tumor model of the MC38 cell line." (PMID 38973608, 2024). "Fibrinogen-like protein 1 (FGL1) is a fibrinogen secreted by hepatocytes, with differential tumor-specific and site-specific expression." (PMID 39252941, 2024). "The interaction between FGL1 and its receptor LAG-3 can result in the reduction of CD8+ tissue-resident memory T cells within tumors, facilitating immune evasion by the tumor." (PMID 38816776, 2024). "CVR/SOR is a powerful combination for tumor repression and enhancing SOR efficiency in HCC by modulating FGL1." (PMID 39466438, 2024). "Recent research has highlighted FGL1 as a ligand for the immune checkpoint LAG-3, showing that its interaction with LAG-3 on T cells induces T cell depletion, facilitating tumor immune evasion." (PMID 38816776, 2024). "The expression of FGL1, a ligand of LAG-3 on the surface of tumor cells, was downregulated in the SAHA group." (PMID 37511510, 2023). "Dual blockade of the FGL1/LAG-3 and PD-1/PD-L1 signaling pathways greatly improved the T-cell killing ability of tumor cells." (PMID 38106403, 2023).
tumor (continued). "Furthermore, the administration of the tumor-penetrating peptide iRGD and ROS-responsive nanoparticles concurrently enhanced the delivery efficiency of siFGL1 and siPD-L1, leading to a significant reduction in the protein levels of FGL1 and PD-L1 in tumor cells." (PMID 38106403, 2023). "Animal experiments have shown that anti-FGL1 or anti-LAG-3 therapies, either as a monotherapy or in combination with anti-PD-1/PD-L1 therapies, can have tumor suppressive effects." (PMID 38098892, 2023). "Besides MHC-II, other ligands of LAG-3 include galectin-3 found on tumor and tumor stromal cells, liver sinusoidal endothelial cell lectin (LSECtin) which is expressed on liver and melanoma cells, and fibrogen-like protein 1 (FGL1) secreted from hepatocytes and tumor cells." (PMID 37304291, 2023). "We next analyzed tumor-infiltrating lymphocytes via flow cytometric analysis and found that FGL1 depletion enhanced the infiltration of IFN-γ+ CD8+/CD4+ and Ki67+ CD8+/CD4+ T cells within the tumor microenvironment." (PMID 37872170, 2023). "By blocking the FGL1/LAG3 interaction, antitumor immunity can be promoted by stimulating tumor-infiltrating lymphocyte activation and expansion in the TME36." (PMID 36765073, 2023). "FGL1 is a novel ligand of LAG3 that results in T-cell depletion and subsequent dysfunction, as well as tumor cell escape from immune surveillance." (PMID 38139416, 2023). "The interaction between FGL1 and LAG-3 mutually promotes tumor immune escape through inhibiting the activation of antigen-specific T cell." (PMID 35958563, 2022). "The FGL-1/LAG3 interaction appears to be an important, MHCII-independent, alternative mechanism for tumor evasion from immune defenses." (PMID 36140182, 2022). "In this review, we present the proliferative role of 15 immune checkpoints, including PD1, PD-L1, FGL1, CD155, CD47, SIRPα, CD276, IDO1, SIGLEC-15, TIM3, Galectin-9, CD70, CD27, 4-1BBL, and HVEM, in tumor progression." (PMID 36358792, 2022). "It is also known that blocking the FGL1-LAG-3 pathway can enhance the activation of T cells and promote anti-tumor immunity." (PMID 35776395, 2022). "Blockade of the FGL1/LAG3 axis with concurrent administration of metformin can enhance T-cell-mediated immune response, improve the tumor microenvironment immunosuppression, and enhance general anti-tumor immunity." (PMID 34975333, 2022). "Thereafter, the expression levels of FGL1 were determined and compared in human HCC cell lines, HCC tissues, peri-tumor tissues and normal liver tissues by western blot analysis." (PMID 35776395, 2022). "Effective inhibition of the FGL1/LAG3 axis can activate tumor T cell immunity, which provides a meaningful direction for tumor immunotherapy." (PMID 34975333, 2022). "Previous studies have confirmed that FGL1 is the main ligand of LAG-3 and its function of inhibiting the anti-tumor T cells by binding to it." (PMID 35273912, 2022). "Blockading the interaction of FGL1 and LAG-3 can trigger T cells and restore anti-tumor immunity by facilitating the TCR/CD28 signaling pathway." (PMID 33867830, 2021). "Current study has displayed that FGL1 is the considerable ligand of the LAG-3 and FGL1-LAG-3 pathway contributes to tumor growth." (PMID 33867830, 2021). "Fibrinogen-like protein 1 (FGL1) is a new major ligand for LAG-3 and it has recently been demonstrated that blocking the FGL1-LAG-3 pathways results in the stimulation of tumour immunity and inhibits tumour growth." (PMID 33995362, 2021). "FGL1 also inhibited the antigen-specific T cell response via LAG-3 in vitro and in vivo, and FGL1-KO enhanced T cell immunity and suppressed tumor growth in a mouse model." (PMID 33633363, 2021). "FGL1 expression was significantly higher in tumor cells (except A549 cells) than in normal BEAS-2B cells (P < 0.01), and among the four tumor cell lines, PC9 and PC9/GR cells exhibited higher FGL1 protein levels than A549 and H1975 cells (P < 0.05)." (PMID 32778129, 2020).